SLPI (secretory leukocyte peptidase inhibitor)
Diseases named in the same sentence as SLPI in open-access papers (continued):
Sharing a sentence is not in itself a finding about the gene and the disease.
asthma (12 papers, 2011 to 2025). "SLPI is an anti-inflammatory gene induced by glucocorticoid in human epithelial cells and low SLPI has been associated with severe asthma in mice and humans." (PMID 29361513, 2018). "More recently, the role of SLPIs in the pathogenesis of asthma has been elucidated in a study, in which sensitized, SLPI-deficient mice were treated with resiquimod, an immune response-modifier from the family of imidazoquinolinamines, known to inhibit allergen-induced Th2 responses." (PMID 21887281, 2011). "In asthma mouse models, both SLPI-knockdown and overexpression experiments have demonstrated a protective role of SLPI in allergic airway inflammation." (PMID 40546642, 2025). "In severe asthma patients, decreased SLPI expression in airway epithelial cells suggests that the loss of SLPI’s protective function contributes to disease pathogenesis." (PMID 40546642, 2025). "Based on the results of these studies, the administration of recombinant SLPI was proposed to represent a promising strategy to treat asthma." (PMID 21887281, 2011). "From these findings, SLPI may be involved in the pathogenesis of protease-mediated Th2-type inflammation, exemplified by asthma, by modulating the innate immune response, principally through attenuation of IL-33 production." (PMID 40546642, 2025). "Low SLPI levels may contribute to the pathogenesis of asthma by promoting Th2 inflammation, highlighting SLPI as a potential therapeutic target in patients with low SLPI expression." (PMID 40546642, 2025). "However, the mRNA of SLPI in the airway epithelial cells in patients with severe asthma was significantly lower compared to those with mild or moderate asthma." (PMID 40546642, 2025). "We studied expression of innervation markers: ubiquitin carboxy-terminal hydrolase L1 (UCHL1/PGP9.5) and occludin (OCLN) as well as genes reported to be associated with asthma: periostin (POSTN), galectin-3 (LGAL3), secretory leukocyte protease inhibitor (SLPI), IL-4, IL-5, IL-13, IL-17." (PMID 35534846, 2022). "High levels of IFN-γ, coupled with reduced levels of secretory leukocyte protease inhibitor (SLPI), are found in patients with severe asthma." (PMID 39664985, 2024). "Studies have shown IFNγ+ CD4+ T cells are more prevalent in the airways in severe asthma versus mild, moderate disease and that IFNγ-induced expression of CXCL10 and down-regulation of SLPI lead to increased AHR and steroid resistance in severe asthma." (PMID 33101299, 2020). "Recent studies have revealed that IFNγ could up-regulate and down-regulate the expression of CXCL10 and SLPI, respectively, which further resulted in increased AHR and steroid resistance in severe asthma." (PMID 35187081, 2022). "Interestingly, SLPI negatively regulates the activation of TGF-β, a key mediator of airway remodeling during asthma progression." (PMID 34777398, 2021).
HIV-1 infection (11 papers, 2008 to 2024). The type species of lentivirus and the etiologic agent of acquired immunodeficiency syndrome (AIDS). "Instead, SLPI appears to block HIV-1 infection after receptor binding, but before reverse transcription." (PMID 38543698, 2024). "SLPI was initially shown to inhibit HIV-1 infection of macrophages through direct interaction with host cell molecules, but not with the virus itself." (PMID 39850816, 2024). "Two members of the whey acidic protein motif family reportedly modulate HIV-1 infection: secretory leukocyte protease inhibitor (SLPI) and trappin-2/elafin." (PMID 28505117, 2017). "Since SLPI was able to disrupt the association between PLSCR1 and CD4, our data suggest that SLPI inhibits HIV-1 infection by modulating the interaction of the CD4 receptor with PLSCRs." (PMID 19333378, 2009). "Here, we confirm that recombinant SLPI is able to inhibit HIV-1 infection of primary T lymphocytes, and show that SLPI can also inhibit the transfer of HIV-1 virions from primary monocyte-derived dendritic cells to autologous T lymphocytes." (PMID 19333378, 2009). "Apart from IAV and SeV, SLPI also inhibits the HIV-1 infection of primary monocytes and PBMCs." (PMID 38543698, 2024). "Additionally, antibodies against A2 or RNA silencing of A2 significantly inhibited HIV-1 infection similar to that of SLPI." (PMID 27863502, 2016). "This antiviral activity is rather due to an interaction with the host cell surface molecule, and annexin II, a membrane-associated protein that is specifically expressed in macrophages, has been recently proposed as a receptor for SLPI that could participate in HIV-1 infection of macrophages." (PMID 19333378, 2009). "In addition, SLPI suppresses bacterial growth and inhibits HIV-1 infection of macrophages." (PMID 18501024, 2008). "AnxA2 is a crucial player in HIV-1 infection, directly interacting with HIV-1 proteins and impacting virus maturation; intriguingly, this process however is inhibited in the presence of SLPI." (PMID 39850816, 2024). "Our in vitro results suggest that treatment with high doses of estrogen and progesterone promotes the expression of host antiviral factors Secretory leukocyte protease inhibitor (SLPI) and Serpin family C member 1 (SERPIN C1) among others produced in response to HIV-1 infection." (PMID 35062299, 2022). "More consistent methodology, exclusion of possible confounding factors such as the characteristics of microbiota, and a focus on likely regulators of HIV-1 infection such as HBD2, SLPI, RANTES, and IFN-α may enhance the consistency between studies." (PMID 29309550, 2018). "It is well established that secretory leukocyte protease inhibitor (SLPI), a protein found in high concentrations in mucosal fluids, protects against HIV-1 infection of macrophages independent of its anti-protease activity." (PMID 27863502, 2016).
lung carcinoma (10 papers, 2006 to 2024). "Expression of SLPI is positively correlated with increased expression of the cell cycle progression factor Cyclin D1, and its causal role in the promotion of malignant behavior has also been demonstrated in lung carcinoma cells stably transfected with human SLPI-expression constructs." (PMID 28679402, 2017). "In our previous study we had shown that WFDC2 was expressed in a number of lung cancer cell lines, some of which also expressed SLPI and elafin." (PMID 16600032, 2006). "Several tumors have shown elevated gene expression levels of SLPI such as ovarian and lung cancer." (PMID 33593445, 2021). "The overexpression of SLPI was involved in metastasis of lung carcinoma 3LL-S cells." (PMID 25954138, 2015). "Additionally, the overexpression of SLPI in lung carcinoma cells showed rapid tumorigenicity and lung metastasis upon subcutaneous inoculation compared to the control cells." (PMID 25954138, 2015). "Overexpression of SLPI in lung cancer cells was shown to lead to a more malignant phenotype." (PMID 25110884, 2014). "Overexpression of secretory leukocyte protease inhibitor (SLPI), which also inhibits trypsin, increases the malignant properties of lung cancer cell lines." (PMID 19384300, 2009).
psoriasis (9 papers, 2016 to 2025). An autoimmune condition characterized by red, well-delineated plaques with silvery scales that are usually on the extensor surfaces and scalp. "Psoriasis etiology has also been linked to pDCs, and LL-37 or other AMPs, including β-defensins or secretory leukocyte protease inhibitor (SLPI)." (PMID 36330530, 2022). "Furthermore, the reduced capacity of SLPI-deficient neutrophils to interact with the vessel wall during the early stages of psoriasis might result from the degradation of trafficking-supporting factors, such as specific adhesion molecules and chemoattractants." (PMID 39928132, 2025). "Our IVM data demonstrate that at early stages of psoriasis development, neutrophils in SLPI KO mice exhibit “jumping behavior” in their interaction with the endothelium." (PMID 39928132, 2025). "During the early stages of psoriasis, neutrophils in WT mice are more efficient than those in SLPI KO mice." (PMID 39928132, 2025). "SLPI protein levels are upregulated in the skin of psoriasis patients compared to healthy individuals, with keratinocytes and neutrophils serving as notable sources of this protein in psoriatic skin." (PMID 39928132, 2025). "Neutrophils numbers in the BM and the bloodstream were comparable between SLPI KO and WT mice over the whole course of experimental psoriasis." (PMID 39928132, 2025). "Among the current 18 members of the WFDC family, the most studied elafin (WFDC14) and secretory leukocyte peptidase inhibitor (SLPI) have been reported to be highly expressed in psoriasis lesions." (PMID 36148224, 2022). "They investigated LDGs and NDNs in psoriasis and found that LDGs had increased staining for NE and reduced staining for secretory leukocyte protease inhibitor (SLPI), an NE inhibitor." (PMID 35141336, 2022). "A role for SLPI in psoriasis was initially suggested by the observation that SLPI is markedly upregulated in the epidermis of psoriasis patients, particularly in keratinocytes." (PMID 27446090, 2016). "The negative regulation of NET formation by SLPI was further supported by an in vivo psoriasis model." (PMID 27446090, 2016). "SLPI is up-regulated in the epidermis of psoriasis patients and in injured skin and is induced during the proliferation of keratinocytes." (PMID 27442430, 2016). "Some insights into this came from the observation that NET-like structures, consisting of DNA, NE, or CatG, and SLPI were present in the affected skin of patients with psoriasis." (PMID 27446090, 2016). "Scenarios where SLPI-regulated serine protease activity contributes to more efficient neutrophil migration may characterize the later stages of neutrophil recruitment in psoriasis." (PMID 39928132, 2025). "To investigate whether SLPI plays a role in neutrophil trafficking in psoriasis, we utilized SLPI knockout (KO) mice and wild-type (WT) littermate controls in an experimental imiquimod (IMQ)-based model of psoriasis-like dermatitis." (PMID 39928132, 2025). "The functional significance of SLPI on NETs in psoriasis remains to be determined." (PMID 27446090, 2016). "For example, excessive NE in the cytosol, unchecked by SLPI, could degrade F-actin, thereby reducing the ability of neutrophils to interact with endothelial cells and migrate out of the vasculature at the early stages of psoriasis." (PMID 39928132, 2025). "Collectively, these findings identify SLPI as an important regulator of neutrophil recruitment to psoriatic skin, acting at multiple levels to influence the efficiency and pattern of neutrophil migration and potentially impacting the course of inflammation in psoriasis." (PMID 39928132, 2025). "Likewise, SLPI was also found to decorate NETs in the affected skin of patients suffering from psoriasis, suggesting that the presence of SLPI on NETs might be functionally relevant." (PMID 27446090, 2016).
psoriasis (continued). "Given the postulated pro-inflammatory and debris-clearing functions of neutrophils, the suppression of early stages of neutrophil skin infiltration in the absence of functional SLPI might have significant pathophysiological consequences for psoriasis." (PMID 39928132, 2025). "Consequently, the impaired migration of neutrophils observed in the absence of SLPI during the early stages of psoriasis might be compensated for at later stages by the release of neutrophils that no longer rely on SLPI function for transmigration." (PMID 39928132, 2025). "Secretory leukocyte protease inhibitor (SLPI), a component of NETs with an inhibitory function on NET formation, may bind to DNA and NE in psoriatic skin lesions and activate the pDCs to produce type 1 interferons (IFN-α, IFN-β, etc.)which regulates autoimmunity in psoriasis." (PMID 31649677, 2019).
viral infections (9 papers, 2012 to 2025). "Beyond protease activity, SLPI has demonstrated the ability to inhibit bacterial and fungal growth and control viral infections." (PMID 40421173, 2025). "Our five genes included three genes overexpressed in bacterial infections (LCN2, PI3, and SLPI) and two overexpressed in viral infections (IFI27 and IFIT2)." (PMID 40843077, 2025). "For example, SLPI (salivary secretory leukocyte protease inhibitor), defensins, sIgA, lactoferrin, and lysosome in the saliva play a protective role against viral infections (e.g. HIV)." (PMID 34858437, 2021). "For instance, the production of IFN-β and secretory leukocyte protease inhibitor (SLPI) by trophoblasts following TLR-3 stimulation in response to a viral infection is thought to interfere with MTCT." (PMID 23223189, 2012). "Additionally, SLPI has been shown to be protective against viral infections such as by HIV-1 or human papillomavirus, including in other mucosal sites." (PMID 40003878, 2025). "The role of SLPI in the mucosal immune response to viral infection has been most extensively explored in viruses of the female reproductive tract, including human immunodeficiency virus (HIV), herpes simplex virus type 2 (HSV-2) (48, –, 50), and human papillomavirus (HPV)." (PMID 39162558, 2024). "Actually, we identified that LCN2, PI3, and SLPI were up-regulated in bacterial infections, and IFI27 and IFIT2 were up-regulated in viral infections in the study, which may be helpful in assisting with the diagnosis of B/V co-infection in children." (PMID 40843077, 2025).
colorectal cancer (7 papers, 2014 to 2026). A primary or metastatic malignant neoplasm that affects the colon or rectum. "Dysregulation of SLPI has been reported in a variety of human cancers including glioblastoma, lung, breast, ovarian and colorectal carcinomas and is associated with tumor aggressiveness and metastatic potential." (PMID 32742768, 2020). "A recent report showed that the overexpression of SLPI in colon cancer tissues could be associated with severe pathological characteristics and suggested its potential role in colorectal cancer cell prognosis." (PMID 36595102, 2023). "However, the pathogenic role of SLPI in colorectal cancer is still unclear." (PMID 32742768, 2020). "This pattern of elevated SLPI and its correlation with poor prognosis has also been reported in other malignancies, including ovarian and colorectal cancers." (PMID 41557653, 2026). "In a previous study, we demonstrated that the developments CRCs were significantly suppressed following the siRNA mediated AKT knockdown and suggested the AKT as a potential target for the treatment of colorectal cancers with high SLPI expression." (PMID 36595102, 2023). "LINC01094 can promote the progression of colorectal cancer by regulating the miR-1266-5p/secretory leukocyte protease inhibitor (SLPI) axis." (PMID 36824662, 2023). "More importantly, we demonstrated that suppressing SLPI can enhance the chemosensitivity of colorectal cancer cells the Cisplatin by activating the Akt/PUMA signaling pathways." (PMID 36595102, 2023). "Aberrant expression of Secretory Leukocyte Protease Inhibitor (SLPI) has been associated with human cancer growth and its suppression was identified as a potential target for anti-cancer drugs, particularly in colorectal cancer." (PMID 36595102, 2023). "Recently, increased SLPI protein expression has been demonstrated in various types of cancer, including colorectal cancer (CRC), gastric cancer, non-small cell lung cancer and ovarian cancer." (PMID 35842496, 2022). "In the present study, we first demonstrated that SLPI was significantly increased in colorectal cancers." (PMID 32742768, 2020). "SLPI knockdown suppressed the survival and invasive potential of colorectal cancer cells via downregulation of AKT." (PMID 32742768, 2020). "Here we showed that SLPI mRNA level was significantly upregulated in colorectal cancer tissues compared to adjacent normal controls." (PMID 32742768, 2020). "In the previous study, SLPI was found overexpressed in colorectal cancer tissues of 296 CRC patients." (PMID 32742768, 2020). "Targeting SLPI by siRNA inhibited proliferation, migration and invasion of colorectal cancer cells lines HT29 and HT116 in vitro." (PMID 32742768, 2020). "In this study, we showed that SLPI knockdown reduced the phosphorylation of AKT in CRC cancer cells, unveiling the potential mechanism of SLPI-mediated pathogenesis in colorectal cancers." (PMID 32742768, 2020). "Here we showed that SLPI transcript level was significantly increased in our archived primary colorectal cancer samples when comparing to normal tissues." (PMID 32742768, 2020). "In the present study, SLPI was found to be highly expressed at the mRNA level in colorectal cancer tissues." (PMID 32742768, 2020). "Together, we found that SLPI transcript level was highly expressed in colorectal cancers compared to their normal counterparts." (PMID 32742768, 2020). "Our data will not only provide novel insights into the role of SLPI during the pathogenesis of colorectal cancer but also shed light into the potential therapeutics for colorectal cancer treatment." (PMID 32742768, 2020). "SLPI knockdown by siRNA effectively reduced the proliferation and metastasis of colorectal cancer cells in vitro." (PMID 32742768, 2020). "More importantly, our present investigation unequivocally demonstrated a previously undescribed association between SLPI and AKT in the pathogenesis of colorectal cancer cells." (PMID 32742768, 2020).